DNAJC10 (DnaJ heat shock protein family (Hsp40) member C10)
Description:
Endoplasmic reticulum disulfide reductase that collaborates directly with the chaperone BIP/HSPA5 (GRP78) to maintain protein quality control by facilitating either the correct folding or the targeted degradation of misfolded proteins. Essential for efficient maturation of newly synthesized polypeptides in the endoplasmic reticulum, binds to substrate proteins and specifically catalyzes the reduction and removal of improper (non-native) disulfide bonds during the folding process. In endoplasmic reticulum-associated degradation (ERAD), DNAJC10 reduces incorrect disulfide bonds specifically in misfolded glycoproteins that have been recognized by EDEM1, a key component of the ERAD pathway, thereby enabling their retrotranslocation and degradation. Promotes apoptotic signaling pathway in response to endoplasmic reticulum stress.
Synonyms: MTHr; ERDJ5; PDIA19; JPDI
Tractability: Antibody: UniProt predicts a signal peptide or a membrane-spanning region. PROTAC: ubiquitination databases record sites on it; its protein half-life has been measured.
Target class: Enzyme; Oxidoreductase
Gene: Protein-coding gene on chromosome 2 (182,715,607 to 182,794,464, forward strand). Ensembl gene ENSG00000077232.
Subcellular location: Endoplasmic reticulum lumen
Pathways (Reactome):
Disease: Maturation of DENV proteins
Gene Ontology:
Molecular function: ATPase binding; Hsp70 protein binding; misfolded protein binding; protein binding; protein-disulfide reductase activity; protein-folding chaperone binding; disulfide oxidoreductase activity; oxidoreductase activity, acting on a sulfur group of donors, disulfide as acceptor; ATPase activator activity; protein-disulfide reductase (glutathione) activity
Biological process: ERAD pathway; intrinsic apoptotic signaling pathway in response to endoplasmic reticulum stress; protein folding in endoplasmic reticulum; response to endoplasmic reticulum stress; IRE1-mediated unfolded protein response
Cellular component: endoplasmic reticulum; endoplasmic reticulum chaperone complex; endoplasmic reticulum lumen; membrane
Genetic constraint (gnomAD): Loss-of-function variants: 49 observed, 57.79 expected, observed/expected ratio (o/e) 0.85, 90% interval 0.67 to 1.08. The upper end of that interval is the gene's LOEUF score, 1.08, which puts it in group 4 of 6, group 1 being the genes least tolerant of losing a copy. Missense variants: 560 observed, 545.81 expected, observed/expected ratio (o/e) 1.03, 90% interval 0.96 to 1.1. Synonymous variants: 175 observed, 180.39 expected, observed/expected ratio (o/e) 0.97, 90% interval 0.86 to 1.1.
Homologues: Orthologues: chimpanzee DNAJC10 (99% identical), macaque DNAJC10 (99% identical), dog DNAJC10 (94% identical), pig DNAJC10 (92% identical), guinea pig DNAJC10 (90% identical), mouse Dnajc10 (90% identical), rat Dnajc10 (90% identical), rabbit DNAJC10 (88% identical), tropical clawed frog dnajc10 (67% identical), zebrafish dnajc10 (66% identical), Caenorhabditis elegans dnj-27 (39% identical), Caenorhabditis elegans Y73B6BL.12 (6% identical). Paralogues in human: DNAJC13 (15% identical), DNAJC16 (13% identical), DNAJC1 (11% identical), DNAJC11 (10% identical), DNAJC21 (10% identical), DNAJC2 (10% identical), DNAJC5 (8% identical), DNAJC5B (8% identical), DNAJC17 (8% identical), DNAJC18 (8% identical), DNAJC14 (8% identical), DNAJC25 (7% identical), and 8 more.